CTSL (cathepsin L)
Diseases named in the same sentence as CTSL in open-access papers (continued):
Sharing a sentence is not in itself a finding about the gene and the disease.
breast carcinoma (continued). "Similar to the pattern of histone cleavage and CTSL activation, KDM4C inhibition or downregulation induced a more pronounced elevation of ROS in KDM4C-amplified basal breast cancer cell lines." (PMID 40457074, 2025). "Further studies are required to decipher the exact mechanisms by which KDM4C–GRHL2 regulates CTSL-mediated histone clipping and to delineate why this function is selected for in KDM4C-amplified basal breast cancers." (PMID 40457074, 2025). "Cathepsin L can also induce SNAIL expression through the Wnt/β-catenin and PI3K−AKT pathways, and regulates EMT in breast cancer and mediates tumor metastasis." (PMID 37398678, 2023). "In the case of cathepsins, CTSB, CTSD, CTSK, CTSL, and CTSS were expressed in all breast cancer cells; however, the mRNA and protein expression of CTSS was much higher in the TNBC cell lines compared to the hormone-responsive cell lines." (PMID 30185799, 2018). "CTSB along with CTSL was found to be overexpressed in HER2 positive cancers and is an important mediator of tumor invasion in this subtype of breast cancer." (PMID 24086418, 2013). "To prove a role for CTSL in KDM4C-blockade-induced histone clipping, we deleted CTSL in five basal breast cancer cell lines (three KDM4C-amplified and two non-amplified) using CRISPR–Cas9." (PMID 40457074, 2025). "Finally, mechanisms that drive the evolution of KDM4C-amplified basal breast cancer to prevent GRHL2 methylation and histone H3 clipping by CTSL would need to be delineated in future studies." (PMID 40457074, 2025). "Cathepsin L mRNA was elevated in the majority of MMTV-p200 CUX1 mammary tumors, however the same was not true for mammary tumors from MMTV-p110 and MMTV-p75 CUX1 transgenic mice." (PMID 24618719, 2014). "Therefore, this immunohistochemical study explores CTSB, CTSL, and CTSS expression levels in a large breast cancer patient cohort, to investigate in which BCa patients the use of cathepsin-targeted NIR FI may have added value." (PMID 39331316, 2024). "The high level of CTSL was correlated with a short RFS (p<0.001), OS (p<0.001), DMFS (p<0.001), PPS (p= 0.0025) in breast cancer from online databases; while in breast cancer with lymph node-positive, high level of CTSL was correlated with a short DMFS (p<0.001) and RFS (p<0.001)." (PMID 37456247, 2023). "Therefore, some breast cancer cases carry a triple biomarker signature—the levels of nuclear VDR, CTSL and TP53BP1 that may be exploited in projecting a treatment strategy in TNBC cases." (PMID 32456160, 2020). "Immunofluorescence assays revealed abnormal expression of CTSL, CTSD, HSPA8, and XRCC4 in CD11b+ cells in tumor tissues than those in paracancerous normal tissues, regardless of breast cancer subtypes." (PMID 41399382, 2026).
viral infection (34 papers, 2020 to 2025). "Thus, the inhibition of CTSL by K777 may result in the loss of cathepsin L-mediated Spike processing, preventing viral infection." (PMID 35889004, 2022). "Inhibition of cathepsin L activity using inhibitors resulted in decreased viral infection, underscoring the role of cathepsin L in ReV coat disassembly." (PMID 40135892, 2025). "The study highlighted the potential of CTSL as an important therapeutic target for SARS-CoV-2, revealing that viral infection amplifies CTSL expression and activity, facilitating viral entry through cleavage of SARS-CoV-2 proteins." (PMID 39897928, 2025). "In Caco-2 cells that equally allow cell entry through both the direct membrane fusion pathway and the endocytosis pathway, inhibition of TMPRSS2 using Camostat and inhibition of cathepsin-L using E-64d blocked viral infection of Caco-2 cells." (PMID 39443717, 2024). "Its inhibition efficiency is further enhanced due to DTBN’s potential to inhibit other host proteins such as PKCα, Cathepsin L and NF-κB, which also play crucial roles in viral infection and replication." (PMID 37176034, 2023). "Host proteases, including furin, TMPRSS2, and CTSL work together to modulate coronavirus S protein-mediated cell fusion, and disturbing the activity of these proteases will effectively inhibit virus infection and proliferation." (PMID 37196033, 2023). "Subsequently, we investigated the role of three enzymes, furin, TMPRSS2, and cathepsin L, during viral infection." (PMID 34818119, 2022). "The viral infection assay using the PsV system proved that CTSL cleavage, especially cleavage at CS-2, is an essential step in SARS-CoV-2 infection." (PMID 35668062, 2022). "CTSL is known to play a role in cancer invasion and metastasis, inflammation, renal disease, diabetes, bone diseases, atherosclerosis, viral infection, as well as other diseases." (PMID 35414771, 2022). "Neither of the compounds inhibited control vesicle stomatitis virus (VSV) PsV virus infection, indicating that the inhibitory effects of CTSL inhibitors depend on SARS-CoV-2 S protein." (PMID 35668062, 2022). "In conclusion, we report that SARS-CoV-2 infection promoted CTSL expression and enzyme activity, which, in turn, enhanced viral infection." (PMID 33774649, 2021). "Because they can inhibit enzymatic activity in the process of invasion and metastasis of tumors, atherosclerosis, renal disease, and viral infection, Cathepsin L has become the potential therapeutic target in modern times." (PMID 34462639, 2021). "Endosomal cysteine proteases (primarily cathepsin L and B) were shown to be important for many viral infections, including severe acute respiratory syndrome (SARS) coronavirus, reovirus, Ebola virus, and murine hepatitis virus 2 infections." (PMID 34072688, 2021). "Furin, TMPRSS2, and cathepsin L enzymes are also important for the early stage of the viral infection." (PMID 32993173, 2020). "Furthermore, we found CTSL-specific inhibitors not only blocked infection of PsV/live virus in cells but also reduced live virus infection of ex vivo lung tissues of both human donors and human ACE2-transgenic mice." (PMID 35668062, 2022). "If these sites are occupied by drugs or antibodies which can block CTSL cleavage, the viral infection could be effectively inhibited." (PMID 35668062, 2022). "Finally, we showed that two CTSL-specific inhibitors exhibited excellent In vivo effects to prevent live virus infection in human ACE2-transgenic mice." (PMID 35668062, 2022). "To verify these observations, we investigated the functions of CTSL during viral infection." (PMID 35668062, 2022). "E-64d, an inhibitor of Cathepsin L (CTSL), can block SARS-CoV-2 pseudovirus infection and has demonstrated potential in the treatment of related viral infections." (PMID 40243525, 2025). "Human CTSL and CAPN1 are important drug targets because they play key roles in viral entry into host cells and virus infection-mediated “cytokine storm”." (PMID 38443334, 2024).
viral infection (continued). "Recent studies have shown that CTSL is highly expressed in the respiratory system, and CTSL inhibitors, such as SID 26681509 and E64d, reduce live viral infection of ex vivo lung tissues of both human donors and human ACE2-transgenic mice." (PMID 39559762, 2024). "Based on the differential expression of virus infection-related genes (ACE2, TMPRSS2, CTSB, CTSL), a recent study claimed that endometrial tissue is likely safe from SARS-CoV-2 cell entry but susceptibility increases with age." (PMID 37142998, 2023). "In laboratory experiments, infection with SARS-CoV-2 pseudovirus was found to increase the expression of CTSL in human cells in vitro and ACE2 in transgenic mice in vivo, demonstrating that overexpression of CTSL enhances viral infection in cells." (PMID 38137381, 2023). "Mechanistic and functional studies revealed the mechanism by which CTSL cleavage is essential for efficient SARS-CoV-2 infection and inhibition of this process efficiently reduced virus infection." (PMID 35668062, 2022). "Proteins such as transmembrane serine protease 2 (TMPRSS2), endoprotease (Furin) and cathepsin L (CTSL) activate the S protein of SARS-CoV-2 to facilitate the fusion of SARS-CoV-2 and IECs membranes, thereby enhancing virus infection and leading to GI symptoms." (PMID 38156008, 2023). "In addition, some host cell proteases such as cathepsin B (CTSB) and cathepsin L (CTSL) can cleave and activate the spike protein, leading to the virus infection." (PMID 35155389, 2022). "Additionally, important elements involved in the activation of viral infection are proteases: transmembrane protease serine 2 (TMPRSS2), cathepsin B (CatB) and cathepsin L (CatL)." (PMID 34200951, 2021). "Understanding how CTSL influences these immune components may offer avenues for optimizing vaccine-induced immunity and enhancing our capacity to combat SARS-CoV-2 and other viral infections." (PMID 38137381, 2023). "Therefore, all these human enzymes, including CTSL, TMPRSS2, and furin, could be involved in the viral infection process, and are most likely to play complementary or compensatory roles in different human tissues." (PMID 35668062, 2022). "Therefore, dual inhibitors targeting host CTSL and CAPN1 might bring broad-spectrum synergistic efficacy to the fight against coronavirus in the future, while reducing excess inflammation to improve symptoms in patients with viral infections." (PMID 38443334, 2024). "Thus, we examined the roles of these cathepsins in viral infection and found that BPIV3 entry required cathepsin B and L. Cara demonstrated that Hendra virus, an important paramyxovirus, leverages the cellular protease cathepsin L to cleave the viral F protein, which elicits fusion activity." (PMID 34072688, 2021). "Consistently, without SARS-CoV-2 infection, ITCH ablation does not exhibit involvement in the maturation of CTSL processing in vT2 cells, further implying that ITCH does not affect the CTSL-dependent virus infection process." (PMID 39677672, 2024). "Genes for the endosomal entry-specific enzyme CTSL and for regulating endolysomal trafficking and membrane fusion, such as NPC1/2 and WDR81/91, were identified and required for Sdel, but not for Sfull virus infection in A549 cells." (PMID 33574281, 2021).
glioma (25 papers, 2007 to 2025). A benign or malignant brain and spinal cord tumor that arises from glial cells (astrocytes, oligodendrocytes, ependymal cells). "In addition to cathepsin L being associated with the radiosensitivity of gliomas, another study also found that cathepsin D was expressed at significantly higher levels in radioresistant clones than in parental cells." (PMID 37398678, 2023). "Similar functions were recently reported for CtsL, a lysosomal protease with overlapping functions with CtsB, in human glioma cells." (PMID 39851495, 2025). "Upon irradiation, CtsL expression levels were significantly increased, resulting in its accumulation within the nuclear compartment of glioma cells." (PMID 39851495, 2025). "Studies have shown that the downregulation of cathepsin L inhibits the proliferation, invasion, and migration of glioma cells." (PMID 38921586, 2024). "Previous studies have suggested that CTSL is required for cell cycle progression of colorectal cancer cells and glioma cells, with a similar observation made in our examination of CTSV in thyroid carcinoma cells." (PMID 38026973, 2023). "In LGG, methionine deprivation to downregulate CTSL and induce proliferation inhibition in glioma cells." (PMID 37660060, 2023). "Silencing cathepsin B and uPAR can inhibit the c-Met pathway and upregulate H2AX, increasing the radiotherapy sensitivity of glioma cells, and the knockdown of cathepsin L has a similar effect." (PMID 37398678, 2023). "CTSL is involved in ionizing radiation-induced epithelial mesenchymal transition and promotes glioma cell invasion and migration via the Akt/GSK-3 β/Snail and CUX1 pathways." (PMID 35855914, 2022). "In the clinical setting, we found that high expression of CTSL was significantly correlated with a short OS in lung cancer and glioma patients." (PMID 35414771, 2022). "We found that a high expression of CTSL was significantly correlated with a short OS in lung cancer (p<0.001) and glioma patients (p<0.001)." (PMID 35414771, 2022). "Cathepsin L was found to be a strong promoter of X-ray-induced glioma cell invasion by regulating Cdc42-mediated cytoskeletal remodeling, a process which was abolished once Cathepsin L was knocked down and Cdc42 levels decreased." (PMID 32089990, 2020). "sDC1 may regulate antigen processing and presentation in gliomas through CTSL or CD4, and thus participate in glioma immune escape." (PMID 37088950, 2023). "Furthermore, the inhibition of Cathepsin L has been found to enhance the radiosensitivity of human glioma U251 cells." (PMID 38003335, 2023). "Notably, by inhibiting cathepsin L, the radiosensitivity of gliomas can also be increased, which provides a new idea for drug combination radiotherapy." (PMID 37398678, 2023). "Similarly, CTSL is involved in regulating the radiosensitivity of glioma cells by acting as an upstream regulator of NF-κB activation, and inhibition of CTSL sensitizes glioma cells to radiation." (PMID 36552871, 2022). "Moreover, high expression of CTSL significantly correlated with a short overall survival (OS) in lung cancer and glioma." (PMID 35414771, 2022). "Protein–protein network interaction analysis showed that SDC1 may regulate antigen processing and presentation through CTSL or CD4 in glioma." (PMID 35669186, 2022). "The upregulated protein Cathepsin L1 in our co-cultured cells, is a lysosomal cysteine protease, which is overexpressed to secret into serum in several cancers, including ovarian cancer, pancreatic neuroendocrine cancer, glioma and others." (PMID 29855483, 2018). "Thus, CTSL expression may be an unfavorable prognostic marker for survival in lung cancer and glioma patients, and a favorable prognostic marker for survival in renal cancer patients." (PMID 35414771, 2022). "Other mitochondrial oxidative-stress-related genes including CTSL, TXNRD2, NUDT1, STOX1, and CYP2E1 have been reported differentially expressed with potential prediction accuracy of glioma." (PMID 39012280, 2024).
glioma (continued). "Our data give credence to the previous finding, which demonstrated the prominent expression of CTSL and CTSB in tumor cells as well as in vascular endothelial cells of glioma." (PMID 31824841, 2019). "For example, antisense constructs to cathepsin L in human glioma cells have been shown to block invasion but not migration." (PMID 17488522, 2007). "The relative labeling percentages (cathepsin B and K: 4%; cathepsin S: 1%) were insignificant, except for cathepsin V (27%), the closest homolog of cathepsin L, relative to cathepsin L. Interestingly, U87-MG glioma cell extracts did not present any cathepsin L for detection with the P3 probe." (PMID 32041276, 2020).
lung carcinoma (22 papers, 2011 to 2025). "Cathepsin L (CTSL), a lysosomal cysteine protease, is increasingly implicated in EMT and tumour progression across multiple cancers, including HNSCC, breast and lung cancer." (PMID 41261048, 2025). "This highlights the complexity of cathepsin L regulation in lung cancer, which requires further investigation to fully understand its contribution to tumor progression." (PMID 40621945, 2025). "We found that CD inhibited CTSL protein levels in a dose dependent manner in the lung cancer cell line A549, triple-negative breast cancer cell line MDA-MB-231, and prostate cancer cell line PC3, respectively." (PMID 35414771, 2022). "Compared to other proteases/proteinases/convertases such as TMPRSS2 and FURIN, the expression of CTSL was higher in both normal lungs and lung cancer samples." (PMID 35414771, 2022). "By further comparison of CTSL, TMPRSS2, and FURIN, all of which are proteinase/protease/convertases 43, 44, we found the expression of CTSL to be the highest in both in normal lungs and lung cancers." (PMID 35414771, 2022). "In line, the injection of lung cancer cells with decreased CTSL expression in mice showed increased apoptosis in tumors compared to mice injected with tumor cells with normal CTSL expression." (PMID 36289617, 2022). "Here, enhanced miRNA-200c expression led to decreased levels of cathepsin L expression and sensitization of cells to paclitaxel-mediated apoptosis in A549 lung cancer cells." (PMID 33233599, 2020). "Meta-analysis showed that lung cancer is associated with a very mild effect on modulation of expression of ACE2 (SMD = −0.16, P = 0.0038) and cathepsin L (SMD = −0.18, P = 0.0011)." (PMID 33425965, 2020). "We indicated here that Egr-1 regulated CTSL-mediated cisplatin resistance in lung cancer by affecting the activity of CTSL promoter." (PMID 31370861, 2019). "We previously demonstrated high expression levels of 32-kDa cathepsin L in colon and lung cancer tissue extracts." (PMID 26674348, 2015). "Previous studies have identified cathepsin L (CTSL)-mediated EMT as a potential target to enhance the efficacy of cisplatin or paclitaxel in lung cancer and other malignancies, revealing that EMT cells exhibit a selective growth advantage in the presence of these drugs." (PMID 40287412, 2025). "Although CTSL expression in HNSC is not as high as in lung cancer, HNSC patients are at significant risk of contracting SARS-CoV-2 infection." (PMID 37292206, 2023). "One cathepsin protease family member found to be categorically important in modulating EMT is cathepsin L, through its ability to translocate to the nucleus in prostate, breast, lung cancer and glioma cells and cleave to Histone H3 and CUX1 proteins resulting in the onset of EMT." (PMID 33233599, 2020). "And the potential regulatory factors of CTSL were consistent in vivo and in human lung cancer." (PMID 31370861, 2019).